MIF (macrophage migration inhibitory factor)
Diseases named in the same sentence as MIF in open-access papers (continued):
Sharing a sentence is not in itself a finding about the gene and the disease.
Sepsis (continued). "Conversely, the lack of DDT had no impact on survival or on the numbers of SPMs in the peritoneal cavity, showing that only MIF is responsible for recruiting CXCR2+ SPMs, thereby promoting inflammation during sepsis." (PMID 36672343, 2023). "Research has shown that serum macrophage inhibitory factor (MIF), an important regulator of innate immunity, is closely related to ALI and the severity of the disease in sepsis patients." (PMID 38076268, 2023). "Curcumin (50 and 200 mg/kg, i.p.)also protected against sepsis-induced acute lung injury in rat model by down-regulating the inflammatory cytokines TNF-α, IL-8, and macrophage migration inhibitory factor (MIF) levels." (PMID 36588685, 2022). "We found an increase in the expression of IL-6, IL-8, IL-10, IL-18, IL-33, IP-10, MIF, MIP1a, MIP1β, MIP3a, LEPTIN, GCSF, MCSF, and ESelectin in sepsis plasma compared to w/o sepsis and HC." (PMID 35681439, 2022). "In sepsis, TNF-α is related to organ dysfunction and increased lethality, while MIF upregulate TLR-4 and TNF-α in macrophages." (PMID 33110395, 2020). "In accordance to the results of Leaver and colleagues, we were able to show raised plasma levels of TRX1 and MIF in patients with SIRS/sepsis, whereby plasma levels of TRX1 and MIF showed a unique correlation." (PMID 20847814, 2010). "The plasma levels of MIF and TRX1 were significantly elevated in patients with severe sepsis or septic shock." (PMID 20847814, 2010). "The present study demonstrates that proinflammatory/~oxidative (Macrophage Migration Inhibitory Factor, MIF) as well as anti-inflammatory/~oxidative (Human Thioredoxin-1, TRX1) agents are significantly raised in patients with severe sepsis and septic shock." (PMID 20847814, 2010). "MIF is found at increased levels in BAL fluids from both LPS induced lung inflammation and polymicrobial sepsis models." (PMID 19413900, 2009). "Our objective was to clarify the relationship between serum MIF and adrenal function in the HPA axis of sepsis patients using the adrenocorticotropic hormone (ACTH) stimulation test." (PMID 20021698, 2009). "Notably, the MIF–(CD74+CXCR4), HLA–KIR, ANXA1–FPR2, and CD99–CD99 signaling pathways were significantly upregulated in sepsis." (PMID 41346577, 2025). "Furthermore, CD8+ T cells and Th cells were found to be involved in sepsis-related ARDS, along with the MIF and CXCL signaling pathways in sepsis-related ARDS." (PMID 38745657, 2024). "Meanwhile, both MIF and CXCL signaling pathways are specific to sepsis-related ARDS." (PMID 38745657, 2024). "There were no statistically significant variations in serum MIF levels between the vehicle and sepsis groups or between the normal and sham groups." (PMID 39144689, 2024). "In sepsis-induced immunosuppression, macrophages exhibit altered cytokine secretion with decreased levels of TNF-α, IL-1β, and IL-12, and increased levels of TGF-β, IL-10, and macrophage migration inhibitory factor (MIF)." (PMID 39372401, 2024). "Our study also found significantly higher serum MIF levels in the sepsis and vehicle groups compared to the normal and sham groups." (PMID 39144689, 2024). "In comparison to the sham group, the sepsis group had significantly higher levels of TLR-4, IL-6, TNF-α, MIF, F2-isoprostane, caspase-3, cTn-I, and CK-MB, while the pre-treated group with Xanthohumol had significantly lower levels (p<0.05) of these markers than the sepsis group." (PMID 37900069, 2023). "Our results suggest that urine MIF can be used as a predictive biomarker in sepsis independently from the kidney function, however, it does not indicate the development of sepsis-associated acute kidney injury." (PMID 36631486, 2023). "MIF plays a role in acute kidney injury (AKI) under various diseased conditions including renal ischemia, toxicity, infection and sepsis, acute graft rejection, post-renal obstruction, immunologically mediated GN, and congenital anomalies of the kidney and urinary tract (CAKUT)." (PMID 35563296, 2022).
Sepsis (continued). "In this study, plasma MIF was higher in neonates with sepsis than in those without sepsis, but the difference was not statistically significant (9862.3 ± 7605.4 vs 7053.9 ± 5750.1 pg/mL, P = .152)." (PMID 36042599, 2022). "Markedly greater elevation in blood MIF level was found in the more severe forms of sepsis and in nonsurvivors than in less severe forms and in survivors with SMDs of 0.84 (CI: 0.45-1.24) and 0.75 (CI: 0.40-1.11), respectively (p < 0.001 for both)." (PMID 33850259, 2021). "According to some literatures on NAFLD, some immune-related loci associated with NAFLD could exhibit some level of pleiotropy influencing sepsis with genes of CD14, IL-6, MIF, TLR4, and TNF." (PMID 34938184, 2021). "Simvastatin treatment was able to reduce the levels of TNF-α, IL-6, MIF, and IL-1β 24 hours after sepsis induction, indicating an important negative immunomodulary effect of simvastatin in this model." (PMID 33110395, 2020). "The inhibition of specific inflammatory cytokines such as a tumor necrosis factor (TNF), migration inhibitory factor (MIF), or high mobility group box (HMGB)-1 provided promising results in experimental sepsis, but, they failed in the clinical trials for sepsis." (PMID 29780390, 2018). "DDT, but not MIF, is a valuable biomarker to predict clinical outcome and sepsis occurrence after burn injury." (PMID 28179905, 2017). "Several studies have shown that MIF is age dependent in other diseases: adults with a low-expressing MIF allele (CATT5) are at high risk of Gram-negative bacterial infections and high-expressing MIF genotypes protect older patients from sepsis mortality." (PMID 27014277, 2016). "The cytokine, macrophage migration inhibitory factor (MIF), is involved in the inflammatory response and is known to regulate the inflammatory response in various inflammatory diseases such as rheumatoid arthritis, pulmonary inflammation, and sepsis." (PMID 25705692, 2015). "Furthermore, ISO-1 and OXIM-11, new small molecule inhibitors of MIF, offered significant protection to mice from CLP-induced sepsis." (PMID 20169062, 2010). "MIF expression is increased in a wide variety of infectious diseases, ranging from viral infections, such as Dengue, HIV and West Nile virus infection, malaria, tuberculosis and various forms of sepsis." (PMID 20169062, 2010). "Finally, the cytokine macrophage migration inhibitory factor (MIF) has been found to be a valuable marker of microbiologically documented infection in patients who have undergone cardiac surgery, and elevated MIF concentrations may be an early indicator of poor outcome in patients with sepsis." (PMID 17362525, 2007). "For example, interleukin (IL)-1, IL-6, IL-12, interferon (IFN)-γ, macrophage migration inhibitory factor (MIF), IL-10, transforming growth factor (TGF)-β, and IL-4 attempt to restore the immunological equilibrium and balance the pro- and anti-inflammatory cascades during sepsis." (PMID 40142568, 2025). "However, the intersection between the sphingolipid metabolism pathway and MIF signaling in the context of sepsis has not been extensively explored." (PMID 40394027, 2025). "Furthermore, the MIF inhibitor also mitigated the effects of CSN6 on the mRNA expression levels of pro-inflammatory cytokines IL-1β, IL-6, TNF-α, and collagen I/III in macrophages in an in vitro sepsis model (n = 6 per group)." (PMID 40595050, 2025). "By using anti-MIF antibodies to neutralize MIF, it has been demonstrated that TNF-α production and the build-up of neutrophils can be reduced, resulting in the alleviation of symptoms and improved prognosis for sepsis-related ARDS patients, ultimately reducing the likelihood of mortality." (PMID 38745657, 2024). "Moreover, we show that urine MIF level can be a valuable prognostic marker of mortality in sepsis, as it was markedly lower in nonsurvivors than in survivors, and it did not change significantly over time in either of the groups." (PMID 36631486, 2023).
Sepsis (continued). "In addition, MIF has been shown to have prognostic value, as blood MIF levels are higher in nonsurviving sepsis patients than in surviving patients and in severer forms of sepsis compared with less severe forms of sepsis." (PMID 38275363, 2023). "None of existing studies on the role of MIF in sepsis report the overall incidence of CRRT in the investigated patients, and none of these studies scrutinized whether CRRT might influence and confound measured MIF levels." (PMID 27313864, 2016). "MCP-1 positively regulates IL-10 but negatively controls macrophage migration inhibitory factor (MIF) in experimental peritoneal sepsis, suggesting an important immunomodulatory role for MCP-1 in controlling the balance between proinflammatory and anti-inflammatory factors in sepsis." (PMID 22272381, 2012). "The pathogenesis of sepsis is attributable, at least in part, to dys-regulated systemic inflammatory responses characterized by excessive accumulation of various proinflammatory mediators such as interleukin (IL)-1, interferon (IFN)-γ, nitric oxide, and macrophage migration inhibitory factor (MIF)." (PMID 17987129, 2007). "Furthermore, in sepsis-induced chronic lung injury in male albino mice models subjected to CLP, it was found that curcumin decreased inflammatory expression of IL-8, TNF-α, MIF in the bronchoalveolar fluid, and pulmonary edema and, as a whole, attenuated chronic lung injury." (PMID 39126050, 2024). "Unfortunately, neither TRX1 nor MIF showed significant differences between the surviving and nonsurviving subgroups of the septic patients and therefore could not be used as an early predictor for survival in patients with severe sepsis or septic shock." (PMID 20847814, 2010). "Most notably, the CXCR2 binding signature motif of MIF is not present in MIF-2, in line with recent findings that MIF, but not MIF-2, recruit macrophages via CXCR2 in a polymicrobial sepsis model." (PMID 40055309, 2025). "The serum MIF kinetics clearly differed between sepsis survivors and nonsurvivors after ICU admission, since in the nonsurvivors serum MIF increased, whereas in survivors it decreased." (PMID 36631486, 2023). "Our results indicate that simvastatin treatment has an important negative immunomodulatory effect in sepsis since it was able to lower the levels of IL-6, TNF-α, IL-1β, and MIF in the peritoneal cavity in our model." (PMID 33110395, 2020). "Analysis of daily MIF levels showed that patients who did not survive septic shock exhibited steadily higher MIF plasma levels and higher MIFAUC compared to those surviving sepsis." (PMID 27313864, 2016).
atherosclerosis (111 papers, 2009 to 2026). A disease characterized by the build-up of fatty material and calcium deposition in the arterial wall resulting in partial or complete occlusion of the arterial lumen. "The MIF/CXCR4 axis is relevant in atherosclerosis, as it has been associated with atherogenic activities of not only monocytes and T cells, but also neutrophils, platelets, and B cells." (PMID 40055309, 2025). "This is a key finding as previous studies have demonstrated an association between circulating MIF and adipose tissue inflammation, development of insulin resistance, β‐cell dysfunction and atherosclerosis." (PMID 39717018, 2025). "Linked to this, MIF levels correlate with the progression to atherosclerosis, and severe hypoglycaemia is a risk factor for an atherosclerotic cardiovascular event." (PMID 39717018, 2025). "This study attempts to detect MIF gene polymorphism in ACS patients as MIF plays a pivotal role in atherosclerosis, which is the main culprit leading to coronary artery disease." (PMID 39439602, 2024). "MIF, a cytokine able to regulate innate and acquired immune responses, is usually associated to atherosclerosis progression, obesity, insulin resistance, and inflammatory diseases." (PMID 31354906, 2019). "In experimental studies, MIF deficiency partially protected from the development of insulin resistance, adipose tissue inflammation, and atherosclerosis in LDL-receptor-deficient and high-fat-fed mice." (PMID 30302090, 2018). "We have shown that MIF is a very potent pathogenic factor in P. gingivalis ATCC 33277-induced atherosclerosis promotion." (PMID 29482504, 2018). "Macrophage migration inhibitory factor (MIF) is an upstream immunoregulatory cytokine associated with the pathogenesis of many inflammatory diseases including atherosclerosis and myocardial infarction." (PMID 30483634, 2017). "Macrophage migration inhibitory factor (MIF) involves the pathogenesis of atherosclerosis (AS) and increased plasma MIF levels in diabetes mellitus (DM) patients are associated with AS." (PMID 25661015, 2015). "In this study, we investigated the effect and its potential mechanism of MIF on STZ-induced diabetes-associated atherosclerosis by using adenovirus-mediated MIF gene interference in mice." (PMID 25661015, 2015). "As the CD74/CXCR2 complex is implicated in MIF-mediated chemotaxis, these receptors are associated with atherosclerosis." (PMID 26175090, 2015). "MIF was shown to be involved in inflammatory atherosclerosis pathogenesis and is implicated in modulation of disease progression." (PMID 25114912, 2014). "Increased circulating levels of MCP-1 and MIF are positively associated with the development of various metabolic diseases such as type 2 diabetes, atherosclerosis, and cardiovascular disease." (PMID 24089589, 2013). "MIF has been implicated in a variety of acute and chronic inflammatory diseases like sepsis, atherosclerosis, rheumatoid arthritis, inflammatory lung disease, or systemic lupus erythematosus." (PMID 23720662, 2013). "Neutralizing MIF bioactivity in atherosclerosis-susceptible mice reduces vascular SMC proliferation and neointimal thickening." (PMID 22363104, 2012). "Genetic deletion and antibody inhibition studies established a causal link between MIF and atherosclerosis." (PMID 21283592, 2011). "In addition, hyperlipidemia can cause atherosclerosis, and MIF is upregulated in atherosclerotic plaques and accelerates the exacerbation of atherosclerosis." (PMID 39247699, 2024). "Old age is a risk factor that is associated with both ACS and MIF gene polymorphism because, as age increases, it accelerates the process of atherosclerosis and plaque formation, which in turn facilitates the release of MIF into the plasma and amplifies the events of plaque rupture and acute MI." (PMID 39439602, 2024).
atherosclerosis (continued). "MIF has been demonstrated to be closely associated with the progressionand severity of atherosclerosis.Animal experiments have shown that MIF is correlated with the thickening of theaortic intima and lipid deposition in mice and in rabbits fed an atherogenic diet." (PMID 30506423, 2019). "We have been suggested that MIF could be a critical contributor for the pathological process of diabetes-associated atherosclerosis." (PMID 25661015, 2015). "Since MIF is an inflammatory mediator and given the role of genetic factors that modify its expression, MIF could contribute to atherosclerosis and susceptibility to ACS." (PMID 25105152, 2014). "However, MIF is involved in the inflammatory processes that underlie atherosclerosis." (PMID 35046995, 2021). "In addition, recent studies have demonstrated that HCY can induce autophagy through the macrophage migration inhibitory factor (MIF)/mTOR signalling pathway, which induces apoptosis/death in human umbilical vein endothelial cells as an independent risk factor for atherosclerosis." (PMID 33030764, 2020). "We identify D-dopachrome tautomerase/macrophage migration-inhibitory factor-2 (MIF-2), a paralog of the cytokine MIF, as an atypical chemokine promoting both atherosclerosis and hepatic lipid accumulation." (PMID 40055309, 2025). "Beyond its involvement in infectious diseases, MIF plays a significant role in various inflammatory and pathological conditions, including asthma, atherosclerosis, cancer, autoimmune diseases, burn injuries, and wound healing." (PMID 41159021, 2025). "MIF proved to be a mediator and marker of the extent of myocardial necrosis, facilitating both atherogenesis and atherosclerosis." (PMID 40426915, 2025). "MIF antagonists have been developed preclinically, inhibit MIF-related monocyte function, and attenuate atherosclerosis." (PMID 38989580, 2024). "MIF's distinctive characteristics and functions make it an essential target for achieving therapeutic atherosclerosis regression, setting it apart from other cytokines." (PMID 39439602, 2024). "Activation of the MIF-CXCR2 and CXCR4 axis promotes leukocyte recruitment, which can exacerbate atherosclerosis mediated by MIF." (PMID 39206196, 2024). "During the course of atherosclerosis, oxidized low-density lipoprotein and angiotensin II induce the production of MIF, which is expressed in both the coronary artery walls and damaged myocardial cells." (PMID 39439602, 2024). "As functional NF-κB–binding sites exist within the MIF promoter, it has been described that oxLDL (oxidized low-density lipoprotein)-mediated MIF induction is NF-κB dependent in atherosclerosis and calcifying processes." (PMID 38989580, 2024). "The balance between macrophage dynamics and MIF's influence determines the progression and severity of atherosclerosis." (PMID 38476376, 2024). "To investigate the functional consequences of MIF/CXCL4L1 heterocomplex formation, we focused on inflammatory and atherosclerosis-relevant activities of MIF." (PMID 36094626, 2022). "Monoclonal antibody NIH/IIID.9 is one of most widely used MIF antibodies, which improved diseases such as atherosclerosis in pre-clinical models." (PMID 35091838, 2022). "Macrophage migration inhibitory factor (MIF) is an important pro-inflammatory factor in atherosclerosis." (PMID 35844519, 2022). "While our focus was on inflammatory/atherosclerosis-relevant cellular effects of MIF predominantly mediated by the MIF chemokine receptor axis, it is possible that MIF/CXCL4L1 heterocomplexation also affects MIF signaling responses through CD74." (PMID 36094626, 2022). "Chemokines are key players in atherosclerosis, such as macrophage migration inhibitory factor (MIF), which regulates upstream signaling of host innate and adaptive immune responses." (PMID 35309326, 2022).